PML (PML nuclear body scaffold)
Diseases named in the same sentence as PML in open-access papers (continued):
Sharing a sentence is not in itself a finding about the gene and the disease.
infection (185 papers, 2006 to 2025). The state of being infected such as from the introduction of a foreign agent such as serum, vaccine, antigenic substance or organism. "SCM mutations diminished colocalization and interaction of HBV core with PML protein during transfection and infection, concomitant with a deficiency of HBV nucleocapsids in nuclear entry, which impaired cccDNA formation." (PMID 37199632, 2023). "We created PML knock-out HFF-Ts, the infection of which resulted in a significant increase in H3K27me2 association with RP5 at 2 hpi over PML-expressing HFF-Ts (wild-type HFF-Ts)." (PMID 38076966, 2023). "Our prior work on BKPyV and PML-NBs demonstrated that infection caused a reorganization of PML-NBs, with an increase in the size and decrease in the number of NBs per nucleus." (PMID 37154756, 2023). "The inability of HSV-1 to initiate productive infection leads to the formation of latency-associated viral DNA-containing PML-NBs (vDCP-NBs), and this pattern is more likely to be initiated if the type I IFN pathway was activated prior to infection (." (PMID 38140525, 2023). "Since deletion and mutation of IE1 resulted in the same reorganization of PML-NBs during infection, both recombinant viruses were utilized for the following experiments and exemplary results are shown." (PMID 35319461, 2022). "This would also fit to the observation that PML cages preferentially appear after infection with high doses of IE1-deficient HCMV." (PMID 35319461, 2022). "Here, we show that PML-NBs undergo a drastic rearrangement into highly enlarged PML cages upon infection with IE1-deficient HCMV." (PMID 35319461, 2022). "Unlike VSV, another Rhabdoviridae family member rabies virus which causes central nervous system dysfunctions does reorganize PML NBs during infection to form larger and more electron-dense aggregates." (PMID 34513832, 2021). "Impairment of de novo SUMOylation coupled to unrestricted activity of SUMO proteases results in massively deSUMOylated population of PML which gets multimerized and associated with the nuclear matrix in response to infection-induced oxidative stress." (PMID 34513832, 2021). "Subsequently, PML has been shown to act as a restriction factor during infection with LCMV as PML knockout mice showed more susceptibility to LCMV infection than their wild type counterparts." (PMID 34513832, 2021). "In contrast to the early recruitment of herpesviral DNA to PML NBs, adenoviral DNA is associated with PML NBs at a relatively late stage of infection (≥4 h)." (PMID 34513832, 2021). "PRR sensing by IFI16 during HSV-1 ΔICP0 infection correlates with IFI16 forming nuclear filaments on vDNA in association with PML following the saturation of PML-NBs under high genome loads." (PMID 32416261, 2020). "PML targeting by IE1 is considered to be crucial for hCMV replication at low multiplicities of infection, in part via counteracting antiviral gene induction linked to the cellular interferon (IFN) response." (PMID 32365141, 2020). "PML appears to act as a sensor of pore formation, as deSUMOylation causes PML multimerization, which in turn triggers the expression of antibacterial cytokines, and transcription factors that help the cell combat infection." (PMID 32380645, 2020). "Our replotted data revealed a highly significant 48.8% increase in the median PML track distance from HAdV RCs during infection with the E2A SUMOylation-deficient virus HAdV E2A SCM." (PMID 32184235, 2020). "Nevertheless, the exact molecular mechanism underlying the subcellular localization of RCs at PML-NBs during infection is not fully understood; likely, the viruses benefit from distinct PML-NB components." (PMID 32184235, 2020). "E2A SCM mutations led to larger distances between RCs and PML tracks than in HAdV wt infection (bottom)." (PMID 32184235, 2020). "RPA1 has been shown to be recruited to HSV-1 and human cytomegalovirus genomes during infection and is sometimes associated with a subset of PML NBs." (PMID 30018111, 2018).
infection (continued). "Taken together, viral genomes are recognized by the cell as DNA damage early during infection and are associated with PML NBs." (PMID 30018111, 2018). "During infection, PML undergoes oxidation-mediated multimerization, associates with the nuclear matrix, and becomes de-SUMOylated due to the pore-forming activity of the Listeria toxin listeriolysin O (LLO)." (PMID 28074026, 2017). "A recent study proposed that PML was an indirect inhibitor of HIV-1 early postentry infection stages through its association with Daxx, a constitutive partner protein in PML NBs." (PMID 28656178, 2017). "We observed that infection with wild-type L. monocytogenes induces a strong multimerization of PML, associated with its global de-SUMOylation." (PMID 28074026, 2017). "An initial study suggested that PML interferes with the early steps of HIV-1 replication in human cells and that HIV infection causes a re-localization of PML from PML-NBs into the cytoplasm shortly after infection." (PMID 26703718, 2015). "In this way, PML expression restrains the propagation of infection and reduces the chance of possible oncogenic mutations due to viral DNA integration into the cell genome." (PMID 23847764, 2013). "Similar to HSV-1, infection with human Cytomegalovirus (HCMV) causes PML-NBs disruption: in this process, the viral protein IE1 is necessary and sufficient to promote this effect." (PMID 23526763, 2013). "To show that the Daxxdisplacement from PML-NBs in the very early infection phase was caused byprotein VI, we analyzed Daxx dissociation from PML-NB also in VI-wt and VI-M1transfected cells." (PMID 22427750, 2012). "We conclude that ICP0 exhibits properties related to those of a STUbL, inducing the rapid loss of SUMO-modified PML followed by widespread proteasome-dependent degradation of SUMO-conjugates during infection in a RING finger-dependent manner." (PMID 21949651, 2011). "It is well established that infection by a variety of viruses is associated with the disruption of PML nuclear bodies and the appearance of PML protein in the cytoplasm." (PMID 18509536, 2008). "As SUMOylation of proteins is known to be a regulator of subcellular and especially nuclear localization, these data indicate that HBV core SUMOylation is a prerequisite not only for its association with PML-NBs but also for nuclear entry during infection per se." (PMID 37199632, 2023). "Moreover, progressive infection with EMCV was found to cause a reduction in PML protein levels both in IFN-treated cells and in PML III-expressing cells." (PMID 34513832, 2021). "Since lower instead of higher cytokine and ISG expression was observed upon infection with the recombinant virus, the authors speculated that disruption of PML bodies may be linked to immune activation." (PMID 33530304, 2021). "The loss of Sp100A protein levels and faulty PML track/RC cooperation in E2A SCM infection might in sum prevent the virus from exploiting beneficial Sp100A capacity." (PMID 32184235, 2020). "PML bodies have been implicated in the antiviral host cell response to infection." (PMID 32365141, 2020). "Consistent with recent studies, infecting HSV-1EdC genomes were readily detectible by click chemistry following virion release into the nucleus and to be stably associated with PML-NBs by 90 minutes post-infection (mpi), prior to their disruption and release by ICP0 by 180 mpi." (PMID 30901352, 2019). "PML-deficient cells are also more prone to infection with rabies virus." (PMID 28656178, 2017). "We found that the inability of HSV-1 to initiate a lytic program at the initial stages of infection led to the formation of latency-associated viral DNA-containing PML-NBs (vDCP-NBs), or another pattern if the type 1 interferon pathway was activated prior to infection." (PMID 27618691, 2016). "Furthermore, we found that many of IFIX interactions were lost following infection, including PML and its associated proteins (DAXX, ATRX, HIRA, etc.)." (PMID 25665578, 2015).
infection (continued). "We therefore asked whether the LTR-mediated transcription of the virus-encoded reporter genes is affected by the presence of PML and whether this influences the outcome of our infection assays." (PMID 26703718, 2015). "In the case of HSV-1, a chance observation provided very strong evidence that this was indeed the case—the viral genomes became very rapidly associated with novel PML NB–like structures in the earliest stages of infection through recruitment of PML NB proteins." (PMID 23825941, 2013). "A dynamicequilibrium of Daxx between PML-NBs and chromatin association may thus govern theresponse status of the host cell upon infection." (PMID 22427750, 2012). "In contrast to virus infected cells, wedid not detect co-precipitated protein VI following cotransfection and IP withdifferent PML isoforms, suggesting an indirect association of PML and proteinVI, presumably bridged by other viral or infection induced factors." (PMID 22427750, 2012). "Furthermore, RNA interference (RNAi) studies have shown that knockdown of Daxx or ATRX can result in a higher infection level of HCMV and also relieve the infection defect of mutant HSV deficient in disrupting PML-NB." (PMID 22102817, 2011). "These conditions avoided variables that might be associated with EGFP tagging of PML or infection with the recombinant virus in which ORF23 capsid protein was expressed as an RFP fusion protein." (PMID 21304940, 2011). "However, they also noted that infection with the mutant PsVs exhibited reduced amounts of L2 protein and viral genomes in the nucleus, suggesting the mutation may affect events upstream of PML accumulation, such as nuclear localization and retention." (PMID 30802273, 2019). "Japanese encephalitis virus (JEV) selectively destabilizes PML isoforms during infection, impairing antiviral immunity." (PMID 41001050, 2025). "ChIP analysis identified PML to bind vDNA (Fig4E), corroborating PML to be an accessory component of viral chromatin upon nuclear infection prior to its degradation by ICP0." (PMID 40834051, 2025). "Importantly, we observed the asymmetric localization of variant histone H3.3 at PML-NBs (white arrows), which likely reflects the transition of histone H3.3/H4 heterodimers deposited at PML-NBs by Daxx into cellular chromatin undergoing active remodelling prior to infection." (PMID 40834051, 2025). "Infection occurs in a Poisson distribution and requires tegument-mediated and proteasome-dependent degradation of intrinsic antiviral factors (e.g., Daxx, PML, BclAF1, etc.)(10, –, 12)." (PMID 39655950, 2025). "In the case of adenovirus type 5, PML bodies are remodeled during infection, and the E4-ORF3 protein interacts with the PML protein, which controls the DNA repair complex." (PMID 39329772, 2024). "We found that the PML spot occupancy, the relative fraction of the nuclear area covered by PML foci, at 24 h of infection was significantly increased in EGFP-positive compared to EGFP-negative cells." (PMID 38485766, 2024). "Many viruses, specifically nuclear-replicating DNA viruses, must antagonize PML-NB-induced heterochromatinization to establish a productive infection." (PMID 38399958, 2024). "In a first article, Giovannoni and colleagues demonstrated that PML restricts DENV (serotype 2) infection in A549 cells." (PMID 39205236, 2024). "Regarding the protein analyses, PML was chosen as the cellular protein, as it plays an important role during infection with HAdVs." (PMID 38675973, 2024). "Infection of HaCaT cells led to the stable enrichment of PML, histone H3 (H3.1/H3.3), and H4 (to a lesser extent) at vDNA." (PMID 39185184, 2024). "Conversely, siRNA-mediated depletion of PML drastically blunted the HP-PsV infection rate, underscoring its contribution to HP-PsV transcription." (PMID 38485766, 2024). "ChIP analysis identified PML to bind vDNA, identifying PML to be an accessory component of viral chromatin upon nuclear infection." (PMID 39185184, 2024).
infection (continued). "IAV infected A549 cells showed minor change in expression of PML at the initial time point; however, it showed significant differences at late phase of infection." (PMID 38166085, 2024). "Infection of PML KO cells led to a reduction in the frequency of Daxx, histone H3, and histone H4 colocalization at vDNA relative to NTC cells." (PMID 39185184, 2024). "Adenoviral DNA-binding protein E2A is SUMOylated during infection and likely connects viral RCs with disrupted PML NBs." (PMID 37127643, 2023). "During the course of infection, nuclear host proteins, including PML, are modified and/or regulated." (PMID 37154756, 2023). "Since PML NBs are often re-organized following infection, it is possible that PyVs induce remodeling of the bodies, in order to affect their functionality (e.g., to avoid activation of the innate immune response)." (PMID 37127643, 2023). "As a component of the viral tegument, pp71 translocates to the nucleus after lytic infection and disrupts major repressive components in PML-NBs, thus enabling transcription of the viral genome." (PMID 37439556, 2023). "For instance, PML and SUMO-1 were reported to be associated with PML NBs during the whole course of infection, whereas Sp100 and Daxx dissociated from NBs in the late phase of infection." (PMID 37127643, 2023). "Nevertheless, one PML NB component, Sp100, has been shown to restrict viral transcription and replication in the later stages of infection." (PMID 37127643, 2023). "In contrast, infection with other PyVs was shown to result in significant alterations and modifications to PML NBs during infection." (PMID 37127643, 2023). "PML is also involved in immune responses to viruses, by regulating signaling pathways during infection, and are targeted by viruses to inhibit this signaling." (PMID 37622121, 2023). "Next, several experiments using pseudoviruses or even viruses provided clear evidence that interactions between viral proteins and PML NBs are required during the early stages of infection." (PMID 37127643, 2023). "Research on the interplay between individual PML NB components and viruses contributes not only to our understanding of the role of PML NBs during infection but also to the elucidation of their physiologic functions in cells." (PMID 37127643, 2023). "Numerous studies have demonstrated the role of PML in antiviral responses, limiting infection by multiple viruses." (PMID 38031162, 2023). "Instead, our results suggest that localization of cccDNA to PML bodies after de novo infection correlates with cccDNA transcription suppression." (PMID 37338350, 2023). "Several components of PML-NBs have been shown to repress HCMV productive infection by restricting IE gene expression in fully-permissive cells." (PMID 37058447, 2023). "Many viruses target PML bodies for disruption via different mechanisms during their infection cycles." (PMID 38009611, 2023). "The current in vitro model of primary renal proximal tubule epithelial (RPTE) cell infection has allowed many discoveries about BKPyV, including the viral life cycle, genetic regulation, and virus-host interactions (including PML-NBs) (16, 31, –, 42)." (PMID 37154756, 2023). "The authors suggested that in this case, the change in PML NBs number was rather a cellular response to the increased level of interferon induced by the infection than a direct consequence of viral replication." (PMID 37127643, 2023). "Beginning at 8 h post infection (hpi), when IE1 was expressed in sufficient amounts, we detected a depletion of SUMOylated PML and a concomitant increase of unmodified PML variants in both HEC-LTT and HFF." (PMID 36233232, 2022). "Even though the expression of L4-100K is beneficial for the infection, the virus is unable to fully relocalize PML-NBs into tracks." (PMID 35699431, 2022).
infection (continued). "As this facilitates initiation of viral immediate-early gene expression, the immediate-early protein 1 (IE1) can be expressed and induces a complete dispersal of PML-NBs within the first hours of infection." (PMID 35319461, 2022). "Further investigation will be needed to examine the role of nuclear p62 in HPV infection or in infections by other viruses that target PML NBs to create a favorable environment for the establishment of viral gene transcription and replication." (PMID 35891458, 2022). "VSV-Sp100A infection in PML−/− and Sp100−/− cells induced significantly higher levels of transcription from RIG-I, OAS-2, IFI16, and IFN-β genes than VSV-GFP did but not transcription from the control gene c-myc." (PMID 36383022, 2022). "MDV/RB1B infection resulted in a six-fold increase in PML mRNA levels at 7 dpi and a three-fold increase at 14 dpi, whereas PML mRNA levels in the bursa upregulated by MDV/CVI988 infection less than two-fold at 7 and 14 dpi." (PMID 36680047, 2022). "(ii) Various viruses have developed strategies to directly target PML body components and modify, dismiss, or disrupt PML body structures during infection (16, –, 24)." (PMID 36383022, 2022). "They show that the recruitment of Sp100, an ISG that is a transcriptional repressor and component of NBs, to viral genomes is delayed compared to PML, likely allowing an initial burst of viral transcription to promote infection." (PMID 36016419, 2022). "Here, we report an interferon- and DNA damage signaling-induced formation of huge PML spheres, referred to as PML cages, which occurs during infection with IE1-deleted HCMV." (PMID 35319461, 2022). "During progression of infection, several PML foci developed into ring-like structures that were often juxtaposed to viral replication centers." (PMID 35319461, 2022). "At different times after infection, cells were harvested for Western blot analysis of PML as well as viral immediate–early (IE1), early (UL44), and late (MCP) proteins as a control for successful infection." (PMID 36233232, 2022). "Nevertheless, considerably higher abundances of HCMV proteins were present at later stages of infection (≥48 hpi) in PML-depleted HEC-LTT compared to control cells." (PMID 36233232, 2022). "There are pro- and antiviral properties ascribed to PML NBs, but it is generally accepted that these bodies and some of the proteins they contain pose a barrier to productive infection by several viruses." (PMID 36373674, 2022). "Nonetheless, we noted augmented levels of viral early and late proteins in PML-depleted HEC-LTT during later phases of infection." (PMID 36233232, 2022). "Quantification of viral DNA by qPCR analysis corroborated this result, as depletion of PML resulted in a comparable increase of intracellular as well as released viral DNA after infection with different virus doses." (PMID 36233232, 2022). "Upon HAdV-wt infection the early viral protein E4orf3 interacts with PML-II mediating the disruption of the dot-like structure into PML tracks." (PMID 35699431, 2022). "Previous immunofluorescence studies of IE2 in HCMV-infected cells suggested that IE2 predominantly localizes to the viral replication compartment in late infection and is enriched near viral genomes at PML bodies even prior to replication onset." (PMID 35579393, 2022). "In contrast, experiments in this study were performed during infection of human mammalian cell lines with a stable expression of the different human PML isoforms under the control of the HSV-1 gD promoter." (PMID 35699431, 2022). "At the same time, the virus modulates cellular antiviral processes and structures such as promyelocytic leukemia nuclear bodies (PML NBs) to enable infection." (PMID 35891458, 2022). "Due to this activity, IE1 induces a complete disruption of PML-NBs within the first hours of infection thereby enabling the onset of lytic HCMV replication." (PMID 36233232, 2022).